FOXM1 (forkhead box M1)
Diseases named in the same sentence as FOXM1 in open-access papers (continued):
Sharing a sentence is not in itself a finding about the gene and the disease.
lymph node metastasis (20 papers, 2011 to 2025). "The transcription factor Forkhead box M1 (FOXM1) overexpression was significantly associated with lymph node metastasis, its downregulation inhibited cell migration and invasion in vitro." (PMID 26755651, 2016). "FoxM1 overexpression was significantly associated with lymph node metastasis (P < 0.001), and tumor recurrence (P < 0.001)." (PMID 25935853, 2015). "With multivariable analysis, FoxM1 expression, lymph node metastasis and age were significantly associated with survival." (PMID 23536876, 2013). "Univariate analysis revealed that tumor size, T stage, lymph node metastasis, vascular invasion, FOXM1 expression, and TNM stage were associated with an inferior survival duration (P < 0.05)." (PMID 24004449, 2013). "The outcome revealed that expression of FoxM1 was associated with lymph node metastasis (OR = 0.33, 95%CI = 0.19–0.62, P < .001), distant metastasis (OR = 0.35, 95%CI = 0.24–0.46, P < .001) and tumor node metastasis (TNM) stage (OR = 0.45, 95%CI = 0.29–0.72, P < .001)." (PMID 30593202, 2018). "In addition, the pooled analysis showed that FoxM1 expression was obviously associated with lymph node metastasis, distant metastasis and TNM stage in CRC." (PMID 30593202, 2018). "This pooled analysis indicated that FoxM1 expression related to lymph node metastasis, distant metastasis, TNM stage and poor prognosis of the CRC patients." (PMID 30593202, 2018). "A higher expression level of FoxM1 was correlated with the presence of multiple tumors (χ2 = 17.030, P < 0.001), tumor diameter > 5 cm (χ2 = 19.503, P < 0.001), lymph node metastasis (χ2 = 13.576, P < 0.001), and advanced TNM stage (χ2 = 6.947, P = 0.008)." (PMID 30580327, 2018). "A univariate Cox analysis implied that FIGO staging, lymph node metastasis, FOXM1, and OTUB1 correlated with survival." (PMID 27167337, 2016). "In our study, we found that FoxM1 expression in tumor specimen was positively associated with several clinicopathological parameters, such as TNM stage, tumor stage and lymph node metastasis." (PMID 23536876, 2013). "FOXM1 overexpression was significantly associated with a high TNM stage, lymph node metastasis, patients with a history of smoking, poor tissue differentiation, poor disease-free survival, low response rate, poor progression-free survival, overall survival, and poor relapse-free survival." (PMID 30992007, 2019). "Our results indicated FOXM1 expression to be significantly associated with lymph node metastasis (P = 0.009), but not with FIGO stage (P = 0.127) and grade (P = 0.298)." (PMID 24885308, 2014). "Elevated FOXM1 levels were associated with lymph node metastasis (P = 0.009), but not with age, FIGO stage, histological grade and histological type." (PMID 24885308, 2014). "However, FoxM1 expression had a remarkably close link with lymph node metastasis (OR = 0.33, 95%CI = 0.19–0.62, P < .001, fixed effect), distant metastasis (OR = 0.35, 95%CI = 0.24–0.46, P < .001, fixed effect) and TNM stage (OR = 0.45, 95%CI = 0.29–0.72, P < .001, random effect)." (PMID 30593202, 2018). "We found that high FoxM1 expression is significantly correlated with primary tumor stage, lymph node metastasis, distant metastasis, TNM stage, and histological grade, suggesting that its expression might be important for the acquirement of malignant potential in ccRCCs." (PMID 23006512, 2012). "Lower levels of FOXO3a, and higher levels of FOXM1, SOX2, or DNMT1 were correlated with shorter survival in the lymph node metastasis positive subgroup." (PMID 31296961, 2020). "Interestingly, for the matched lymph node metastasis, the opposite trend was observed with decreased ESR1 topic and increased FOXM1 topic, showcasing transcriptional plasticity within a patient." (PMID 36318267, 2022). "Moreover, high levels of FOXM1, SOX2, and DNMT1 were correlated with high histological grade, advanced clinical stage, and lymph node metastasis." (PMID 31296961, 2020).
lymph node metastasis (continued). "Among these 60 patients, the patients (n = 50) with positive lymph node metastases had higher FoxM1 mRNA expression when compared with patients with negative lymph node metastases (n = 10), instead of age, sex, and pathological grade of GCA." (PMID 32551039, 2020). "The expression of FOXM1 in patients with lymph node metastasis was significantly higher than in patients without lymph node metastasis (P = 0.009)." (PMID 24885308, 2014). "Those patients with lymph node metastasis had a significantly higher expression of FoxM1 compared with those patients without lymph node metastasis (P<0.0001)." (PMID 23536876, 2013). "If strong FOXM1 expression is confirmed in surgical patients that have early stage I/II cancer and no lymph node metastasis or well/moderately differentiated carcinoma, adjuvant therapy and frequent follow-up might be suggested." (PMID 30992007, 2019). "Additionally, 5 out of 6 cases with lymph node metastasis showed over-expression of FOXM1 (data not shown)." (PMID 21858223, 2011).
myeloma (19 papers, 2018 to 2025). "FOXM1-deficient myeloma cells proliferated more slowly than their parental counterparts that contained normal levels of FOXM1, henceforth called FOXM1N and used as control." (PMID 35794249, 2022). "Using FOXM1-deficient myeloma cells as principal experimental model system, we find that FOXM1 increases glucose uptake, lactate output, and oxygen consumption in myeloma." (PMID 35794249, 2022). "In newly diagnosed myeloma patients, the FOXM1 gene is associated with high risk, which, upon tumor relapse, experiences further increases in most cases." (PMID 32679860, 2020). "We now know that FOXM1 is a high-risk myeloma gene in newly diagnosed patients that undergoes further upregulation in the majority of cases upon tumor relapse." (PMID 30463534, 2018). "Increased FOXM1 levels in FOXM1Hi myeloma cells caused partial resistance to Bz (1.9–5.6 fold) and Dox (1.5–2.9 fold) in vitro, using FOXM1N myeloma as control." (PMID 30463534, 2018). "Two independent human myeloma cell lines (HMCLs) containing normal levels of FOXM1 (FOXM1N) or elevated levels of lentivirus-encoded FOXM1 (FOXM1Hi) were employed to determine FOXM1-dependent changes in cell proliferation, survival, efflux-pump activity, and drug sensitivity." (PMID 30463534, 2018). "The overexpression of PBX1 induces FOXM1 upregulation, thereby influencing the biologic behavior of the disease and the proliferation of myeloma cells." (PMID 41226583, 2025). "We demonstrate that the novel 1,1-diarylethylene small-compound FOXM1 inhibitor, NB73, suppresses myeloma in cell culture and human-in-mouse xenografts using a mechanism that includes enhanced proteasomal FOXM1 degradation." (PMID 35794249, 2022). "Our results on FOXM1-dependent activation of myeloma metabolism agree with evidence that metabolic reprogramming, a hallmark of human cancer, is important for MM." (PMID 35794249, 2022). "In agreement with that, clonogenicity increased upon forced expression of FOXM1 in MM1.S myeloma cells that contain low amounts of the transcription factor (lane 6)." (PMID 35794249, 2022). "The finding that the IC50 of NB73 in myeloma cells that harbor low amounts of FOXM1 (MM1.S and XG-7) was approximately 2-fold higher than that in OPM2 and Delta47 cells supports the contention that the inhibitor exhibits specificity." (PMID 35794249, 2022). "In conclusion, this study has provided clear-cut evidence that FOXM1 governs myeloma metabolism by upregulating glycolysis and bioenergy supply." (PMID 35794249, 2022). "The synergy between FOXM1 inhibition (NB73) and HSP90 inhibition (GDA) suggests a new treatment approach for patients with myeloma expressing ample amounts of FOXM1." (PMID 35794249, 2022). "In sum, these findings demonstrate that in myeloma cells FOXM1 regulates glycolysis at the transcriptional level." (PMID 35794249, 2022). "The proliferation and survival enhancing effect of FOXM1 was also evident in assessments of clonogenic myeloma growth in soft agar and progression of intravenous myeloma cell xenografts in NSG mice." (PMID 35794249, 2022). "Although the mechanism by which proteasome inhibitors reduce FOXM1 protein levels is unclear, bortezomib, a first-generation proteasome inhibitor approved for the treatment of multiple myeloma, is reported to suppresses FOXM1 mRNA and protein." (PMID 35955438, 2022). "To address this knowledge gap, we used Western blotting to measure FOXM1 protein levels in 11 human myeloma cell lines (HMCLs)." (PMID 35794249, 2022). "In sum, these findings strongly indicated that FOXM1 promotes myeloma cell glycolysis and energy production." (PMID 35794249, 2022). "We evaluated NB73, a newly developed small-drug inhibitor of FOXM1, to facilitate the bench-to-bedside translation of FOXM1-targeted myeloma therapy." (PMID 35794249, 2022).
myeloma (continued). "FOXM1 is a promising molecular target in newly diagnosed high-risk myeloma (HRMM) and relapsed/refractory myeloma (RRMM), but the mechanism with which FOXM1 promotes plasma cell neoplasia is poorly understood." (PMID 35794249, 2022). "FOXM1 is a positive regulator of myeloma cell metabolism and strongly influences the bioenergetics pathways of glycolysis and oxidative phosphorylation." (PMID 36612063, 2022). "Here we show that FOXM1 is a positive regulator of myeloma metabolism that greatly impacts the bioenergetic pathways of glycolysis and oxidative phosphorylation (OxPhos)." (PMID 35794249, 2022). "We show that FOXM1 is a positive regulator of myeloma metabolism with major impact on the bioenergetic pathways of glycolysis and oxidative phosphorylation (OxPhos)." (PMID 35794249, 2022). "The family with sequence similarity 72 member D (FAM72D) is also known as GCUD2; it is a poor prognostic gene of myeloma and control cell proliferation and survival in the FOXM1 transcription factor network." (PMID 32566639, 2020). "Regarding the various biological roles ascribed to the FOXM1 in MM, it resembles some well-recognized transcription factors of myeloma, such as myelocytomatosis oncoprotein (MYC) and interferon regulatory factor 4 (IRF4)." (PMID 32679860, 2020). "In a study of plasma cell myeloma, overexpression of FOXM1 in cell lines resulted in a significantly higher tumor volume of xenografts formed in mice." (PMID 31390744, 2019). "Upregulation of FOXM1 rendered human myeloma cell lines (HMCLs) in continuous in vitro culture partially resistant to the PI, bortezomib (Bz), and the DNA intercalator, doxorubicin (Dox)." (PMID 30463534, 2018). "FOXM1 message was evaluated in 88 paired myeloma samples from patients with nMM and rMM, using gene expression microarrays as measurement tool." (PMID 30463534, 2018). "To confirm the co-regulation of FOXM1 protein levels and the tumor suppressor, Rb, in myeloma, we performed triplicate Western analyses of paired FOXM1Hi and FOXM1N tumors (left)." (PMID 30463534, 2018). "The results presented above were in line with genetic evidence gleaned from transcriptomic studies using microarrays, indicating that FOXM1 promotes myeloma proliferation." (PMID 30463534, 2018). "In agreement with that was the in vivo result that enforced expression of FOXM1 in a HMCL designated CAG reduced the sensitivity of myeloma-in-mouse xenografts to Bz." (PMID 30463534, 2018). "Our recent work has implicated the cyclin-dependent kinase 6 (CDK6) / retinoblastoma (Rb) axis in the mechanism by which FOXM1 promotes myeloma." (PMID 30463534, 2018). "We found that enforced expression of FOXM1 renders myeloma partially resistant to both drugs, as evidenced by half-maximal inhibitory concentrations (IC50) that, in case of Bz, were 5.6-fold (CAG) and 1.9-fold (XG1) higher in FOXM1Hi than FOXM1N cells (left)." (PMID 30463534, 2018). "Next, we used eFluxx-ID Gold MDR analysis to demonstrate that upregulation of FOXM1 results in enhanced ABC-transporter efflux-pump activity in myeloma." (PMID 30463534, 2018). "Indeed, NB73 has been shown to be effective in inhibiting FOXM1 in myeloma cells in both cell culture and a xenograft mouse model." (PMID 40149290, 2025). "Future studies will reveal whether any of these compounds synergize with NB73 in hampering FOXM1-driven myeloma." (PMID 35794249, 2022). "The transcription factor, forkhead box M1 (FOXM1), has been implicated in the natural history and outcome of newly diagnosed high-risk myeloma (HRMM) and relapsed/refractory myeloma (RRMM), but the mechanism with which FOXM1 promotes the growth of neoplastic plasma cells is poorly understood." (PMID 35794249, 2022). "Because our previous work suggested that in order to be fully effective FOXM1 inhibition must be combined with inhibition of other players in the FOXM1 myeloma network, we searched for lead compounds that may synergize with NB73 in myeloma." (PMID 35794249, 2022).
myeloma (continued). "Elucidating these pathways in greater depth may lead to new, metabolically targeted myeloma therapies that include FOXM1 inhibition." (PMID 35794249, 2022). "The FOXM1 inhibitor NB73 slowed myeloma progression both in vitro and in vivo." (PMID 36612063, 2022). "The myeloma-promoting role of FOXM1 has been documented, but whether FOXM1 is essential in myeloma has not yet been established." (PMID 35794249, 2022). "Additionally, it has shown that the small-compound FOXM1 inhibitor, NB73, suppresses myeloma by virtue of promoting FOXM1 degradation." (PMID 35794249, 2022). "We sought to determine whether upregulation of FOXM1 may be a prognosticator of dismal survival in the Multiple Myeloma Research Foundation (MMRF) CoMMpass study (NCT01454297)." (PMID 35794249, 2022). "In vitro, the upregulation of FOXM1 has been shown to increase drug resistance in myeloma." (PMID 32679860, 2020). "We also detected additive loss of IKAROS/IKZF1 and the myeloma pro‐survival factors IRF4 and FOXM1." (PMID 31714026, 2020). "The result of this study adds strength to the contention that the therapeutic targeting of FOXM1 may benefit patients with myeloma in which the transcription factor is strongly expressed." (PMID 30463534, 2018). "FOXM1’s interaction in myeloma cells with NEK2 (NIMA-related kinase 2) and the CDK4/6-Rb-E2F axis is of interest from a therapeutic viewpoint because CDK inhibition may be effective in myeloma." (PMID 30463534, 2018). "The main finding of this study is experimental evidence for a role of FOXM1 in advanced myeloma." (PMID 30463534, 2018). "Furthermore, HSP90 inhibitor GDA cooperates with NB73 by destabilizing FOXM1 in myeloma." (PMID 35794249, 2022). "Drugs from this group reduce the expression of FOXM1, thus limiting the proliferation of neoplastic cells, but its increased expression was observed in myeloma cells in relapsed patients, which may indicate the involvement of this gene in the development of resistance to BTZ." (PMID 35269574, 2022). "A variety of molecularly targeted chemo-sensitization approaches of this sort are pursued in myeloma – all attempting to build on findings in B-ALL that demonstrate that drug resistance in malignant B lymphocytes may be overcome by suppression of FOXM1." (PMID 30463534, 2018). "Also assessed was the hypothesis that increased levels of FOXM1 diminish the sensitivity of myeloma cells to commonly used myeloma drugs, such as the proteasome inhibitor bortezomib (Bz) and the DNA intercalator doxorubicin (Dox)." (PMID 30463534, 2018). "Here, we demonstrate that the novel small-compound FOXM1 inhibitor NB73 binds and destabilizes FOXM1 in myeloma cells and suppresses myeloma in cell culture and human-in-mouse xenografts." (PMID 35794249, 2022). "Inspired by findings that heat shock protein 90 (HSP90) physically interacts with and stabilizes FOXM1 in myeloma cells, we show that HSP90 inhibitor, geldanamycin (GDA), collaborates with NB73 in slowing down myeloma." (PMID 35794249, 2022). "Consistent with the FOXM1-stabilizing chaperone function of heat shock protein 90 (HSP90), the HSP90 inhibitor, geldanamycin, collaborates with NB73 in slowing down myeloma." (PMID 35794249, 2022). "FOXM1’s interaction with NIMA-related kinase 2 (NEK2) and the CDK4/6-Rb-E2F axis, in myeloma cells, is considered to be useful from a therapeutic aspect, because CDK inhibition is thought to be effective in myeloma treatment." (PMID 32679860, 2020). "The cooperativity of NB73 and GDA suggests that combined FOXM1 and HSP90 inhibition might be a new treatment option for FOXM1-driven HRMM and RRMM, two critical unmet needs in myeloma." (PMID 35794249, 2022). "In addition to FOXM1, LDHA is upregulated in myeloma via HIF1A (hypoxia inducible factor 1 subunit alpha) and PPARGC1B (peroxisome proliferator-activated receptor gamma coactivator 1 beta)." (PMID 35794249, 2022).
myeloma (continued). "Dampening glucose import using the HIV protease inhibitor ritonavir and inhibiting PFK (phosphofructokinase) or ENO (enolase) have also been evaluated as experimental myeloma therapy, albeit with limited success and not in the context of upregulated FOXM1." (PMID 35794249, 2022). "Enhancement of FOXM1 degradation by GDA suggests that co-inhibition of FOXM1 and HSP90 may be a promising precision medicine approach to treating myeloma that contains elevated levels of FOXM1." (PMID 35794249, 2022). "Whether FOXM1 is similarly important for the putative myeloma stem cell is not known as the elusiveness of this cell stands in the way of resolving the issue." (PMID 35794249, 2022). "FOXM1-inhibiting antibiotics of this sort demonstrate broad cancer-suppressing activity in the low micromolar concentration range in solid and liquid tumors – including myeloma – yet are not suitable for use in humans due to severe toxicity issues." (PMID 35794249, 2022). "Although the molecular mechanism by which FOXM1 promotes drug resistance in myeloma has not yet been elucidated, FOXM1-dependent increases in cell proliferation, NEK2 (NIMA related kinase 2)-dependent CIN (chromosomal instability) and ABC-transporter drug-pump activity may be involved." (PMID 30463534, 2018).